MIR299 (microRNA 299)
Synonyms: hsa-mir-299; MIRN299; mir-299
Gene: MicroRNA gene on chromosome 14 (101,023,794 to 101,023,856, forward strand). Ensembl gene ENSG00000207749.
Gene Ontology:
Biological process: miRNA-mediated post-transcriptional gene silencing
Cellular component: RISC complex
Homologues: Orthologues: chimpanzee ptr-mir-299 (98% identical), mouse Mir299a (97% identical), guinea pig MIR299 (95% identical), pig ssc-mir-299 (95% identical).